CRP (C-reactive protein)
Diseases named in the same sentence as CRP in open-access papers (continued):
Sharing a sentence is not in itself a finding about the gene and the disease.
pulmonary TB (continued). "Thus, we sought to validate the performance of the MASC assay as well as of other acute-phase reactants such as C-reactive protein (CRP) and ferritin among children who were undergoing outpatient evaluation for pulmonary TB in Karachi, Pakistan, in comparison to healthy control children." (PMID 32024709, 2020). "When only the individuals with pulmonary TB were compared to those with ORD, significant differences were observed for SAA, CRP, VEGFR3, RANTES, Pentraxin3, Ferritin, CCL18, MPO, GDF-15, MMP-1, PDGF-BB, Procalcitonin, MDC, Myoglobin, and VCAM-1." (PMID 33732236, 2021). "As highlighted previously, our findings indicate that monitoring acute phase parameters (ESR, CRP), Th1 cytokines (IL-2) and anti-inflammatory (IL-4) may help understanding the multidimensionality of immunopathology in TB and point to novel potential therapeutic targets for pulmonary TB." (PMID 27494953, 2016). "An elevated platelet count, CRP, and ESR but not MPV were shown to be significantly associated with pulmonary TB cases." (PMID 41041335, 2025). "Furthermore, most of the studies demonstrating raised levels of ferritin, CRP, and ADA in TB and a decrease with treatment have focused on pulmonary TB with relatively few reports on these markers in EPTB cases." (PMID 39623309, 2024). "Importantly, blood CRP measurements show significantly inferior accuracy to blood RNA biomarkers in EPTB, and to that previously reported accuracy in pulmonary TB." (PMID 38946942, 2024). "Fourth, our study focused solely on pulmonary TB and thus did not explore the performance of CRP for detecting extrapulmonary TB." (PMID 39446791, 2024). "The AUROC of CRP for discriminating culture-positive pulmonary TB among Ultra-negative participants was 0·66 (95%CI 0·57–0·75)." (PMID 36375640, 2023). "This suggests a potential role for CRP in resolving false positive Ultra results: a positive CRP together with a positive, non-trace Ultra has high sensitivity for culture-confirmed pulmonary TB, together with a trace-positive Ultra sensitivity was moderate." (PMID 36375640, 2023). "An individual participant data meta-analysis evaluated CRP as a screening test for pulmonary TB among PLHIV, irrespective of signs and symptoms, describing 83% sensitivity (95%CI 79–86) and 67% specificity (95%CI 60–73; n = 3187) in that setting." (PMID 36375640, 2023). "Among adults attending primary care with TB-related symptoms and pulmonary TB prevalence up to 27%, CRP 10 mg/L provided >95% probability that a screened individual does not have pulmonary TB (95%CI 92–97%)." (PMID 36375640, 2023). "We assessed the accuracy of the WHO symptom screen, GeneXpert MTB/RIF (Xpert), and candidate biomarkers including C-reactive protein (CRP), hemoglobin, erythrocyte sedimentation rate (ESR), and monocyte-to-lymphocyte ratio for identifying pulmonary tuberculosis." (PMID 33632173, 2021). "Newly diagnosed smear positive pulmonary tuberculosis/immunological and autophagy biomarkers (T cell, monocyte and dendritic cell functions ESAT-6/CFP-10, Culture filtrate Protein, estimation of C reactive protein, tumor necrosis factor-alpha and other cytokines)." (PMID 32410999, 2020). "CRP and SAA1 were included in the verification panel because these are considered established major acute-phase effectors and are expected to increase in individuals with pulmonary TB." (PMID 32780727, 2020). "When the concentrations of the six available markers (CRP, IFN-γ, IP-10, CFH, Apo-A1, and SAA), from the adult pulmonary TB seven-marker signature were evaluated in serum samples from children with TBM vs. those without TBM individually, significant differences were obtained for CFH only." (PMID 31612118, 2019). "Multivariate analysis showed that a low CRP level (OR 0.808; 95% CI 0.674–0.967; p = 0.020) significantly predicted non-cavity pulmonary tuberculosis." (PMID 31344108, 2019).
pulmonary TB (continued). "Patients with pulmonary TB also exhibited significantly higher serum CRP levels than LTBI patients (p < 0.001) and non-TB, non-LTBI subjects (p < 0.001)." (PMID 29844416, 2018). "A trend toward higher on-treatment mortality rate was also noted in pulmonary TB cases with high serum CRP levels, but statistical significance was not reached (23.3% vs. 9.3%, p = 0.080)." (PMID 29844416, 2018). "Both CRP and ESR are considered as prognostic indicators in patients with pulmonary TB." (PMID 27311307, 2016). "Previous studies had reported that CRP and ESR could be considered as severity indicators of pulmonary TB." (PMID 27311307, 2016). "If so, then despite recent interest in adopting point-of-care CRP as a triage test for TB12,15,38 we may expect that blood RNA biomarkers provide a more consistent performance for the range of disease manifestations beyond pulmonary TB." (PMID 38946942, 2024). "Sato and colleagues reported that in cured patients with active pulmonary TB, serum vitamin D levels showed a significantly negative correlation with time duration until sputum conversion, as well as platelets count and CRP and a significant positive correlation with serum albumin." (PMID 38982373, 2024). "However, previous studies have only looked at CRP as a screening tool for pulmonary tuberculosis and have failed to assess its utility in the screening of extra pulmonary tuberculosis." (PMID 35806852, 2022). "On the contrary, in BCG-treated monkeys, CRP remained low in most of animals and did not correlate with LRG (r = 0.156), We also assessed the association between biomarkers and the severity of pulmonary TB." (PMID 32099022, 2020). "CRP achieved the WHO-defined sensitivity, but not specificity, targets for a triage test for pulmonary TB and showed evidence of clinical utility among symptomatic outpatients, irrespective of HIV status." (PMID 36375640, 2023).
sacroiliitis (70 papers, 2010 to 2025). "Several studies have confirmed that elevated C-reactive protein is positively associated with the presence of sacroiliitis, C-reactive protein is expected to be a new diagnostic marker." (PMID 37065189, 2023). "Signs of active inflammation, such as elevated C-reactive protein (CRP) levels or evidence of sacroiliitis on magnetic resonance imaging (MRI) predispose to a more rapid progression of structural damage and can predict conversion of nr-axSpA to AS." (PMID 37250652, 2023). "In a 1-year prospective study, hip bone loss was found to be associated with elevated baseline CRP in a post hoc analysis and with sacroiliitis diagnosed with MRI." (PMID 33861786, 2021). "In this study, the increased CRP levels resulting from disease activity were significantly associated with the presence of sacroiliitis (p = 0.028)." (PMID 32665619, 2020). "They found that the strongest predictor of progression of radiographic sacroiliitis by at least one grade was an elevated CRP at baseline, which carried an associated increased risk of 3.65." (PMID 29273055, 2017). "The presence of deep BME on SIJ MRI, increased CRP levels, and the severity of sacroiliitis on X-ray were independent risk factors for low BMD in patients with axSpA." (PMID 26931505, 2016). "The presence of deep BME on SIJ MRI, increased CRP levels, and severity of sacroiliitis on X-ray were independent risk factors for low BMD." (PMID 26931505, 2016). "The results also showed that severe acute sacroiliitis on MRI, increased CRP levels, and radiographic sacroiliitis are associated with an increased risk of low BMD." (PMID 26931505, 2016). "Multivariate analysis identified the presence of deep BME on SIJ MRI, increased CRP, and sacroiliitis on X-ray as risk factors for low BMD (OR = 5.6, 14.6, and 2.5, respectively)." (PMID 26931505, 2016). "Anti-tumor necrosis factor (TNF) agents can also be administered systemically to address SIJ pain, but their use is recommended only under specific conditions, such as persistent high disease activity, elevated CRP levels, or positive imaging for sacroiliitis." (PMID 40004824, 2025). "Disease activity in either of them is measured via C-reactive protein (CRP) levels or magnetic resonance imaging (MRI) of the pelvis showing sacroiliitis due to the presence of bone marrow edema." (PMID 41284991, 2025). "Particularly, in spondyloarthritis, platelet indices are more central to the pathology of sacroiliitis, and CRP, which is currently used, is a generalized marker of inflammation." (PMID 41284991, 2025). "These included the presence of inflammatory back pain, progressive imaging-confirmed sacroiliitis, and elevated CRP levels." (PMID 40364197, 2025). "In this case, the 36-year-old man was definitively diagnosed with AS based on his history of recurrent lumbosacral pain, MRI findings indicating sacroiliitis, a positive HLA-B27 test result, and elevated levels of CRP and ESR." (PMID 40979853, 2025). "For instance, the authors found increased high sensitivity CRP levels in patients with sacroiliitis confirmed by MRI compared to the controls." (PMID 37871023, 2023). "This case had severe pain, and her CRP was very high, leading us to include pyogenic sacroiliitis in the entry diagnosis." (PMID 35573053, 2022). "These criteria combine physical examination, presence of sacroiliitis on imaging and laboratory tests for human leukocyte antigen B27 (HLA–B27) and C-reactive protein (CRP)." (PMID 36844956, 2022). "The patient's workup showed elevated erythrocyte sedimentation rate (ESR) and C-reactive protein (CRP), bilateral symmetrical sacroiliitis on magnetic resonance imaging (MRI), and multiple bony lesions on bone scintigraphy." (PMID 35371846, 2022). "An observational study in a cohort of patients with early axSpA has also demonstrated the limited predictive capacity of CRP, with sacroiliitis on MRI identified as the only predictor of TNFi response." (PMID 34715908, 2021).
sacroiliitis (continued). "The highest treatment differences between secukinumab and placebo were observed in patients with both elevated CRP and evidence of sacroiliitis on MRI." (PMID 34481517, 2021). "This is consistent with the GESPIC study that reported that an elevated CRP level at baseline was a strong positive predictor of radiographic sacroiliitis progression in adult-onset nr-axSpA." (PMID 34862311, 2021). "Compared with other predictive analyses, C-axSpAnd enrolled patients with elevated CRP and/or active sacroiliitis on MRI, which reflects current ASAS-EULAR recommendations for the initiation of TNFi therapy in axSpA." (PMID 34715908, 2021). "Selected variables were IBP, HLA B27, CRP, SpA features, positive sacroiliitis on radiography, SPBME ≥2, WPBME ≥2, erosion, fat metaplasia, backfill, sclerosis ≥1, and the different associations of the SP/WPBME ≥2 with the Tw1CL." (PMID 33347471, 2020). "Sacroiliitis is the most important clinical manifestation of AS.However,there is high variability in detecting the activity of sacroiliitis by clinical methods such as C-reactive protein (CRP) and erythrocyte sedimentation rate (ESR)." (PMID 33234145, 2020). "In the German Spondyloarthritis Inception Cohort (GESPIC), elevated levels of CRP, a marker of systemic inflammation, were a strong positive predictor of sacroiliitis progression in AS patients." (PMID 30768617, 2019). "After logistic regression including other cofounding variables such as gender, age, HLA-B27 presence, CRP, ASDAS-CRP and NSAIDs intake, rs1004819 genotype remained independently associated with MRI sacroiliitis." (PMID 30646942, 2019). "In one prior study in women with AS, older age, longer disease duration, severe sacroiliitis, elevated CRP and baseline syndesmophytes were predictors of the development of new syndesmophytes in the lumbar spine over 2 years in univariate analyses." (PMID 30075808, 2018). "This would be particularly important for those with sacroiliitis on MRI and normal CRP, but high disease activity, suggesting a potential benefit from anti-TNF therapy." (PMID 30217232, 2018). "Univariate logistic regression analysis identified the presence of deep BME on SIJ MRI, elevated ESR and CRP, grade of radiographic sacroiliitis, and spinal radiographic progression (mSASSS ≥ 2) as being associated with low BMD." (PMID 26931505, 2016). "Increased CRP (OR: 14.6; 95% CI: 2.5–85.0; p = 0.003) and grade of radiographic sacroiliitis on X-ray (OR: 2.5; 95% CI: 1.1–5.8; p = 0.036) were also associated with low BMD." (PMID 26931505, 2016). "In multivariate analysis, DKK-1 serum levels were associated with male gender (p = 0.03), CRP level (p = 0.006), SOST serum level (p = 0.002) and presence of sacroiliitis on radiography (p = 0.05)." (PMID 26313358, 2015). "In these patients, male sex was predictive of radiographic sacroiliitis and >1 syndesmophyte and CRP ≤6 mg/L for >1 syndesmophyte and >1 bridging syndesmophyte." (PMID 22650358, 2012). "Thus, we observed a lower frequency of HLA-B*35 among patients with radiologically confirmed sacroiliitis grade ≥ 2, whereas its frequency was elevated in the cohort characterized by inflammatory biomarkers (elevated CRP or ESR)." (PMID 40806743, 2025). "Notably, B*08-B*18 was more frequent in patients with radiographic sacroiliitis grade ≥ 2, while B*35-B*51 was more frequent in those with confirmed systemic inflammation, as indicated by elevated CRP or ESR levels." (PMID 40806743, 2025). "The B*08-B*18 genotype was particularly associated with more advanced structural damage, as reflected by radiographic sacroiliitis grade ≥ 2, whereas B*35-B*51 was more prevalent among patients exhibiting systemic inflammation, indicated by elevated CRP or ESR levels." (PMID 40806743, 2025).
sacroiliitis (continued). "Our study findings indicate that a vast majority of rheumatologists adhere to these recommendations, with only a small percentage suggesting biologic therapy for nr-axSpA patients in the absence of clinical or objective signs of inflammation, such as elevated CRP or sacroiliitis on MRI." (PMID 38803407, 2024). "At T0, fetuin-A levels were significantly higher in non-smokers, in patients with heel enthesitis and in those with a family history of axSpA; fetuin-A levels at T24 were higher in females, in patients with higher ESR or CRP at T0 and in those with radiographic sacroiliitis at T0." (PMID 36834615, 2023). "The highest treatment differences between secukinumab and placebo were observed in patients with both elevated CRP levels and evidence of sacroiliitis on MRI, and in male patients, whereas the difference was minimal between HLA-B27 positive and negative subgroups." (PMID 34481517, 2021). "Elevated CRP and active sacroiliitis on MRI are the strongest predictors for such a progression." (PMID 28630526, 2017). "However, all patients in RAPID-axSpA with normal CRP values had demonstrated sacroiliitis on MRI at baseline; therefore, it is unclear whether CRP values in patients with active nr-axSpA who do not show active inflammation on MRI behave in a same manner." (PMID 30217232, 2018). "Previous studies have shown that smoking status, alcohol use, HLAB27 positivity, CRP, poor responsiveness to NSAIDs, and inflammation at magnetic resonance imaging (MRI) of the sacroiliac joint could predict the radiographic sacroiliitis progression in patients with AxSpA." (PMID 28464949, 2017). "The ASAS-EULAR recommendations list C-reactive protein (CRP) and MRI sacroiliitis as factors that increase the likelihood of response to tumour necrosis factor inhibitors (TNFi)." (PMID 38743252, 2024). "AxSpA patients with degraded bone/low TBS group had higher CRP levels, disease activity scores (including PGA, BASDAI, BASFI, BASMI, and ASDAS), and prevalence of grade 4 sacroiliitis and current NSAIDs use than those in normal and high TBS groups." (PMID 37758825, 2023). "The positive predictive value increases to 12% if elevated C-Reactive Protein (CRP) levels and active sacroiliitis on MRI are present." (PMID 37000839, 2023). "Multivariate analysis revealed a significant positive association of DKK-1 serum level and female gender (p = 0.03), CRP level (p = 0.006), SOST serum level (p = 0.002) and the presence of sacroiliitis on radiography (p = 0.05)." (PMID 26313358, 2015). "At that time the elevated levels of C-reactive protein (CRP): 14.2 mg/L in the blood in addition to her clinical presentation and Magnetic Resonance Imaging (MRI) led to the diagnosis of sacroiliitis and spondylodiscitis, for which she received intravenous antibiotics (clindamycin and gentamicin)." (PMID 41153294, 2025). "Active sacroiliitis on MRI, ESR, and CRP were considered as proxies of disease activity instead." (PMID 37390068, 2023). "A total of 317 patients with nr-axSpA and elevated CRP and/or active sacroiliitis on MRI (MRI positive or MRI negative) were enrolled in C-axSpAnd and were randomised to either CZP 200 mg Q2W (n = 159) plus NBBM or placebo (n = 158) plus NBBM." (PMID 34715908, 2021). "Sacroiliitis and non-sacroiliitis patients differed significantly with regard to CRP, but not with respect to ESR." (PMID 32665619, 2020). "In the GESPIC, elevated baseline CRP was identified as a strong predictor (OR 4.7 in a multivariable model) of the radiographic sacroiliitis progression of non-radiographic axial spondyloarthritis to AS after 2 years of follow-up." (PMID 30768617, 2019). "Current biological disease markers in axSpA (human leukocyte antigen (HLA)-B27, C-reactive protein (CRP), sacroiliitis shown on radiography or magnetic resonance imaging (MRI)) have insufficient diagnostic properties to rely on for making a diagnosis, impeding early diagnosis and treatment." (PMID 29490705, 2018).